CTBP1 (C-terminal binding protein 1)
Description:
Corepressor targeting diverse transcription regulators such as GLIS2 or BCL6. Has dehydrogenase activity. Involved in controlling the equilibrium between tubular and stacked structures in the Golgi complex. Functions in brown adipose tissue (BAT) differentiation.
Synonyms: BARS; HADDTS
Tractability: Small molecule: a structure with a bound ligand is known. PROTAC: UniProt records ubiquitination sites on it; ubiquitination databases record sites on it; its protein half-life has been measured.
Gene: Protein-coding gene on chromosome 4 (1,211,434 to 1,250,333, reverse strand). Ensembl gene ENSG00000159692.
Subcellular location: Cytoplasm; Nucleus
Subcellular location (Human Protein Atlas): Nucleoplasm
Pathways (Reactome):
Signal Transduction: Deactivation of the beta-catenin transactivating complex; Repression of WNT target genes
Cell-Cell communication: Negative Regulation of CDH1 Gene Transcription
Disease: Signaling by TCF7L2 mutants
Metabolism of proteins: SUMOylation of transcription cofactors
Gene Ontology:
Molecular function: DNA-binding transcription factor binding; identical protein binding; NAD binding; oxidoreductase activity, acting on the CH-OH group of donors, NAD or NADP as acceptor; protein binding; protein domain specific binding; transcription corepressor activity; transcription corepressor binding; transcription coactivator activity; transcription coregulator binding; chromatin binding; lncRNA binding; RNA polymerase II-specific DNA-binding transcription factor binding
Biological process: negative regulation of transcription by RNA polymerase II; regulation of cell cycle; negative regulation of cell population proliferation; negative regulation of DNA-templated transcription; negative regulation of Ras protein signal transduction; regulation of transcription by RNA polymerase II; viral genome replication; white fat cell differentiation; positive regulation of DNA-templated transcription; synaptic vesicle clustering; synaptic vesicle endocytosis
Cellular component: nucleoplasm; nucleus; transcription repressor complex; cytoplasm; GABA-ergic synapse; glutamatergic synapse; presynaptic active zone cytoplasmic component
Genetic constraint (gnomAD): Loss-of-function variants: 11 observed, 34.16 expected, observed/expected ratio (o/e) 0.32, 90% interval 0.2 to 0.53. The synonymous counts are far from expectation, so gnomAD's model fits this gene poorly and the ratio says little. Missense variants: 393 observed, 536.58 expected, observed/expected ratio (o/e) 0.73, 90% interval 0.67 to 0.8. Synonymous variants: 324 observed, 247.14 expected, observed/expected ratio (o/e) 1.31, 90% interval 1.2 to 1.44.
Homologues: Orthologues: chimpanzee CTBP1 (99% identical), macaque CTBP1 (99% identical), mouse Ctbp1 (99% identical), rat Ctbp1 (98% identical), dog CTBP1 (98% identical), pig CTBP1 (97% identical), tropical clawed frog ctbp1 (94% identical), zebrafish CTBP1 (91% identical), zebrafish ctbp1 (83% identical), guinea pig CTBP1 (79% identical), Drosophila melanogaster CtBP (66% identical), Caenorhabditis elegans ctbp-1 (49% identical), and 3 more. Paralogues in human: CTBP2 (80% identical), PHGDH (26% identical), GRHPR (21% identical).
Diseases named in the same sentence as CTBP1 in open-access papers:
CTBP1 is named in the same sentence as 107 diseases in open-access papers, as found by Europe PMC text mining. Sharing a sentence is not in itself a finding about the gene and the disease. The quoted sentences say what the papers report.
breast carcinoma (47 papers, 2011 to 2025). "In breast cancer, the expression of serine protease 2 induced by C-terminal-binding protein 1 is associated with tumor progression and metastasis." (PMID 37022096, 2023). "Altogether, these results demonstrate that CtBP1 is implicated in cell proliferation since its depletion induces cell cycle arrest and inhibits cell proliferation in breast cancer cells." (PMID 26933806, 2016). "Previous preclinical and clinical studies demonstrated that CtBP1 overexpression associates with poor breast cancer prognostic." (PMID 26933806, 2016). "Furthermore, in breast cancer Bcl-3 stabilizes CtBP1, causing a decrease in CtBP1-dependent pro-apoptotic genes p21 and NOXA." (PMID 39327470, 2024). "In addition, CtBP1 protein expression in breast cancer patients is associated with lower median survival." (PMID 26933806, 2016). "In summary, we identified CtBP1 as a new molecular link that associates MeS and breast cancer." (PMID 26933806, 2016). "Our work improves this finding showing that CtBP1 might confer a worse outcome for patients with breast cancer associated to MeS." (PMID 26933806, 2016). "Considering the biological function of the gene itself, we believe that CTBP1 can promote the brain metastasis of breast cancer, but there is limited research on this topic." (PMID 40500539, 2025). "In breast cancer, CTBP1/2 acts as an epigenetic effector downstream of elevated NADH, suggesting that CTBP2 is involved in promoting energy production in cancer cells." (PMID 38698344, 2024). "C-terminal binding protein 1 (CtBP1), a transcription corepressor, confers breast tumor cells resistance to cisplatin by Rad51 upregulation in both breast cancer and gastric cancer cells." (PMID 35875146, 2022). "Meanwhile, miR-137 inhibits proliferation and migration of breast cancer cells by targeting CtBP1 and the estrogen receptor ERR." (PMID 34539732, 2021). "Most recently, Zhao and colleagues found that CtBP1 promotes metastasis of breast cancer through activating TGF-β signaling." (PMID 31929749, 2020). "Let-7e-3p has been identified as one of the miRNAs involved in breast cancer development that is regulated by C-terminal binding protein 1 (CTBP1) and metabolic syndrome." (PMID 31769433, 2019). "Using this available data, 126 breast cancer patients were quantitively stratified according to CtBP1, CtBP2, and LSD1 nuclear expression into low, medium and high terciles of expression." (PMID 31534138, 2019). "CTBP1 mediates metastasis in multiple cancers, including prostate cancer, breast cancer and melanoma, but its role in ovarian cancer metastasis has not been reported." (PMID 28977939, 2017). "To elucidate the role of CTBP1 in tumor progression and metastasis in breast cancer patients, we analyzed several patient datasets." (PMID 27409664, 2016). "There are numerous in vitro studies supporting that CtBP1 regulates multiple genes related to tumorigenesis, tumor progression and metastasis in breast cancer cells." (PMID 26933806, 2016). "Previously, it was reported that CtBP1 regulates miR-124 in prostate cancer; however, this is the first report showing that CtBP1 regulates multiple miRNAs in breast cancer." (PMID 26933806, 2016).
breast carcinoma (continued). "We analyzed CtBP1 expression levels in different breast cancer cell lines: MCF7, T-47D, MDA-MB-231, MDA-MB-453, MDA-MB-468 and BT-474." (PMID 26933806, 2016). "High concentrations (10 mM) of MTOB, an intermediate in the methionine salvage pathway, are required to antogonize the CtBP-regulated activities in colon and breast cancer, while NSC95397 has been shown to be a weaker CtBP inhibitor than MTOB and also not being selective for CtBP1 activities." (PMID 38711119, 2024). "We previously reported that PA transcriptionally controlled expression of p21 and E-cadherin via direct binding to the dehydrogenase domain of C-terminal binding protein 1(CtBP1), a transcriptional co-repressor, to inhibit growth and migration of breast cancer cells." (PMID 37024907, 2023). "AS of CTBP1 plays essential roles in chemoresistance in breast cancer." (PMID 35860803, 2022). "Finally, integrated correlation of gene expression in breast cancer patients with nuclear levels of CtBP1 and LSD1, reveals new potential therapeutic vulnerabilities." (PMID 31534138, 2019). "In addition, low CTBP1 correlated with better response and longer distant metastasis-free survival of breast cancer patients treated with chemotherapy." (PMID 27409664, 2016). "CtBP1 expression in breast cancer tumors might be a powerful tool for diagnosis, prognosis and therapy in a subgroup of breast cancer patients with MeS." (PMID 26933806, 2016). "However, the effect of CtBP1 hyperactivation by MeS in breast cancer development and progression remains unexplored." (PMID 26933806, 2016). "CtBP1 expression induced breast cancer cells proliferation by inhibiting cell cycle arrest." (PMID 26933806, 2016). "Triple negative breast cancer cells showed CtBP1 increased expression levels compared to luminals." (PMID 26933806, 2016). "Additionally, through analyzing mRNA and miRNA expression profile dataset GSE40059, we observed an inverse correlation between miR-644a and CTBP1 expression in 11 different breast cancer cell lines." (PMID 27409664, 2016). "More recently, a new interaction partner of Bcl-3, CtBP1, was found in breast cancer cells." (PMID 22195643, 2011). "Interestingly, expression of Bcl-3 and CtBP1 is strongly correlated in breast cancer samples." (PMID 22195643, 2011). "In breast cancer, FBXO32 mediates CtBP1 ubiquitination and nuclear translocation to promote epithelial-to-mesenchymal transition (EMT)." (PMID 38643215, 2024). "CtBP1 (C-terminal binding protein 1) transactivates RAD51 and confers cisplatin resistance to breast cancer cells." (PMID 34716319, 2021). "Overall, all these data confirm that CTBP1 is a major functional target of miR-644a mediating drug resistance and EMT in breast cancer." (PMID 27409664, 2016). "Note that FBXO32 was reported to bind and regulate CTBP1 in breast cancer cells, but we identified CTBP1 neither in the proteomic analyses nor in classical co-immunoprecipitation experiments (not shown)." (PMID 33462405, 2021). "We found that Stage 2 and 3 breast cancers where cancer starts to spread to nearby lymph nodes feature higher CTBP1 levels compared to Stage 1 breast cancer which has no or only microscopic invasion smaller than 1 mm." (PMID 27409664, 2016). "Interestingly, Snail2 has been described to repress several genes through recruitment of CtBP1 and HDAC1 to their proximal promoters in human breast carcinoma cells but the Snail2 regulatory regions involved in those interactions have yet to be defined." (PMID 22567133, 2012).
breast carcinoma (continued). "Furthermore, FOXP2 harbors a binding domain for the co-repressor CtBP1 (C-Terminal Binding Protein-1) which has been experimentally validated and may be involved as a tumor suppressor in oncogenic processes through interaction with the BRCA1/2 breast cancer oncofactors." (PMID 29725501, 2018).
prostate carcinoma (20 papers, 2013 to 2025). A carcinoma that arises from epithelial cells of the prostate gland. "Overexpression of CTBP1 has been observed in metastatic prostate cancer cells and leads to its mislocalization." (PMID 40096084, 2025). "Recent studies have found that CtBP1 is highly expressed and mislocalized in metastatic prostate cancer, and reducing the expression level of CtBP1 can significantly inhibit prostate cancer proliferation and metastasis in vivo and in vitro." (PMID 38932279, 2024). "As prostate cancer progresses in the setting of MetS, CTBP1 increases, resulting in repression of miR-205-5p together with upregulation of oncomiRs, like: miR-19b-3p, miR-29c-3p, miR-30b-5p, miR-301a-3p, miR-454-3p." (PMID 34199293, 2021). "Previously, we reported C-terminal binding protein 1 (CTBP1), a transcriptional co-repressor of tumor suppressor genes, as a molecular link between MeS and BrCa or prostate cancer." (PMID 29568399, 2018). "Down-regulation of miR-34a/b/c suppressed tumor formation in colorectal cancer, while over-expression of miR-34a in aggressive prostate cancers (PCAs) cells reduced proliferation and colony formation by CtBP1\miR-34a\STMN1\GDF15 pathway." (PMID 30319976, 2018). "The 5th ranked genes, CTBP1, was shown to inhibit proliferation in prostate cancer cell lines, suggesting a potential role as an oncogene." (PMID 29017547, 2017). "Recently, we have reported that gene transcription regulation by C-terminal binding protein 1 (CtBP1) provides a molecular link among MeS, CtBP1 function and tumor growth in prostate cancer." (PMID 26933806, 2016). "This patient has a rare variant (p.P421L) of CtBP1, a coregulator of BRCA1, which has been linked to risk of prostate cancer." (PMID 26485759, 2015). "We had also shown that transcriptional co-repressor CtBP1 plays a role in prostate cancer progression by down regulating multiple tumor suppressor genes." (PMID 25115393, 2014). "MiR-124 in turn is negatively regulated by transcriptional repressors EZH2 and CtBP1, both of which are overexpressed in aggressive prostate cancer." (PMID 25115393, 2014). "MiR-124 in turn is regulated by transcriptional repressor Enhancer of Zeste Homolog 2 (Drosophila) EZH2 and transcriptional co-repressor C-terminal binding protein 1 (CtBP1), genes that are overexpressed in aggressive prostate cancer." (PMID 25115393, 2014). "Another group at the University of Michigan recently reported that CtBP1 was overexpressed and mislocated in metastatic prostate cancer and suggested a prominent role for CtBP1 in the progression of prostate cancer." (PMID 23762064, 2013). "CTBP1 expression is generally upregulated in prostate cancer, and they could be promising targets for therapeutic options of prostate cancer." (PMID 34796209, 2021). "In prostate cancer, CTBP1 regulates a cluster of miRNAs that target cell adhesion." (PMID 34199293, 2021). "Accumulation evidence indicates that lncRNAs can change the transcriptional activity of specific target genes via interaction with proteins; for example, the ncRNA Ctbp1 has been shown to increase the transcriptional activity of androgen receptors in prostate cancer cells." (PMID 27572135, 2016). "In addition, Genomatix MatInspector analysis showed that transcriptional repressor EZH2 and co-repressor CtBP1, both of which are overexpressed in prostate cancer, contain HIF1α binding sites at their promoters." (PMID 25115393, 2014). "Our study is corroborated through Oncomine co-expression analysis that shows CtBP1, EZH2 and P4HA1 are co- and over-expressed in prostate carcinoma samples." (PMID 25115393, 2014). "Additionally, we show here that transcriptional co-repressor CtBP1, which has been shown to repress LCN2 (Lipocalin-2) and ARHGDIB (Rho GDP Dissociation Inhibitor Beta) expression in prostate cancer, regulates miR-124 expression." (PMID 25115393, 2014).
melanoma (14 papers, 2009 to 2025). A malignant, usually aggressive tumor composed of atypical, neoplastic melanocytes. "It included CTBP1, whose decreased expression has been associated with migratory, invasive potential of melanoma cells." (PMID 20932292, 2010). "Details on genes regulated by CtBP1 associated to melanoma development Genes with TCF/LEF binding sites in their promoter were analyzed." (PMID 19216735, 2009). "Recently, we described the loss of CtBP1 expression in melanoma." (PMID 19216735, 2009). "In melanoma cells loss of full length CtBP1 expression, a known co-repressor involved in gene regulation with several other transcription factors, is accompanied by induction of a CtBP1 splice variant." (PMID 19216735, 2009). "It therefore appears that loss of the CtBP1 co-repressor function may be a critical event in the pathogenesis of melanoma." (PMID 19216735, 2009). "Interestingly, Western blot and RT-PCR studies revealed the existence of a CtBP1 splice variant (CtBP1splice) in melanoma cells." (PMID 19216735, 2009). "It, therefore, appears that loss of the CtBP1 co-repressor function may be a critical event in the pathogenesis of melanoma, however, important tumor promoting effects of CtBP can be achieved by CtBP1splice." (PMID 19216735, 2009). "Similar cytoplasmic re-localization of CtBP1/BARS has been observed in murine melanoma B16F10 cells and in other tumors: cervical (HeLa cells) and breast (MCF7 cells), both tumors transcriptionally regulated by CtBP1/BARS as well." (PMID 38711119, 2024). "Functionally, Comp. compromises the regulatory network of genes associated with multiple “cancer hallmarks” and malignant transformation under the specific control of CtBP1/BARS in melanoma cells." (PMID 38711119, 2024). "Altogether, this Comp.11-mediated control of CtBP1/BARS cellular activities impairs melanoma tumor growth in mouse models." (PMID 38711119, 2024). "This higher CtBP1/BARS protein level commits cell proliferation and genome instability endorsing melanoma initiation and progression by CtBP1/BARS-mediated transcriptional repression of CDKN2A gene and Brca1 gene." (PMID 38711119, 2024). "The p16INK4a protein controls the melanoma cell-cycle progression, and its transcriptional induction is under the control of the C-terminal binding protein 1 (CtBP1)." (PMID 38711119, 2024). "Taken together, these data support a distinct and innovative mechanism of Comp. in inhibiting melanoma growth through its selective binding to CtBP1/BARS." (PMID 38711119, 2024). "Previously, CtBP1 overexpression has been demonstrated to be important for suppressing tumor suppressor genes and promoting melanoma development." (PMID 29879296, 2018). "Fusion of the E1A peptide at the N terminus with CPP facilitates cell entry and CtBP1 inhibition in H1299 lung carcinoma and A375 melanoma cells, overcoming the first hurdle." (PMID 29879296, 2018). "The human melanoma cell line A375 was chosen because of its highly aggressive oncogenic phenotypes that are dependent upon CtBP1 overexpression." (PMID 29879296, 2018). "Further analyses revealed CtBP1 to be strongly expressed in primary melanocytes whereas in melanoma cells in vitro and in vivo full length CtBP1 expression is lost or strongly downregulated suggesting an important role of CtBP1 in melanoma progression." (PMID 19216735, 2009). "Downregulation of these genes by CtBP1 was confirmed by transient transfection of CtBP1 into the melanoma cell line (Col1A2: 0.31, FAT: 0.52, SLC26A2: 0.72, VCAN: 0.75 compared to mock control set as 1)." (PMID 19216735, 2009). "To find cellular mechanisms regulated by CtBP1 in melanoma we generated CtBP1 expressing melanoma cells by stable transfection to subsequently perform functional assays." (PMID 19216735, 2009). "In summary, this study revealed that reduction of CtBP1 expression is correlated with migratory, invasive potential of melanoma cells." (PMID 19216735, 2009).